TLR4 (toll like receptor 4)
Diseases named in the same sentence as TLR4 in open-access papers (continued):
Sharing a sentence is not in itself a finding about the gene and the disease.
atherosclerosis (continued). "Heat shock protein 60 (HSP60) not only plays a pivotal role in the development of several maladies with strong inflammatory components but also HSP60 peptides possess anti-inflammatory properties in TLR4-mediated diseases, such as diabetes, arthritis, and atherosclerosis." (PMID 35433873, 2022). "The TLR4 signaling pathway is a potential anti-inflammatory and anti-atherosclerosis target." (PMID 36204316, 2022). "TLRs, specifically TLR4, have an established role in multiple cardiovascular pathophysiologies, including our recent work demonstrating that LPS drives proteoglycan modifications as an initiating step in atherosclerosis." (PMID 35122536, 2022). "Increased expression of TLR-4 and upregulation of its ligands stimulate atherosclerosis." (PMID 36147190, 2022). "Furthermore, it has been proven that TLR-4 can be regulated under the “hygiene theory,” as would occur in atherosclerosis-prone airway branches." (PMID 34621380, 2021). "Moreover, CD14 and TLR4 play a vital role in initiating sterile inflammation related to atherosclerosis." (PMID 34829669, 2021). "Previous studies suggested that TLR4 plays a role in atherosclerosis." (PMID 34539804, 2021). "Thus, our results showed that GDF-15 suppressed proinflammatory response induced by oxLDL and attenuated atherosclerosis initiation as well as progression by downregulating TLR4." (PMID 34539804, 2021). "Besides, aerobic exercise and statins can induce the expression of miR-146a, thereby reducing the TRAF and TLR4 signaling pathways and vascular inflammatory damage in atherosclerosis, confirming the protective effect of aerobic exercise on vascular diseases." (PMID 34099844, 2021). "There is substantial evidence that gut microbiota, particularly Escherichia coli lipopolysaccharide leaking from the gut, may influence the development of atherosclerosis via Toll-like receptor 4 (TLR-4)-mediated oxidative stress." (PMID 33806236, 2021). "Also, it has been observed that inhibition of TLR4 activation can reduce plaque size and macrophage infiltration into atherosclerosis lesions." (PMID 32378144, 2021). "Overall, TLR4 might be a critical part of the pre-atherosclerotic changes to inhibit the formation of atherosclerosis." (PMID 34580342, 2021). "MiR-182-5p can inhibit oxidative stress and apoptosis by inactivating TLR4 in atherosclerosis." (PMID 34234781, 2021). "Our finding suggested that TLR4 may mediate the inflammatory process of atherosclerosis in smokers and smoking cessation may have an anti-inflammatory effect by reducing the level of TLR4 and the production of inflammatory cytokines." (PMID 33995400, 2021). "Statins, as the most commonly prescribed drugs for hypercholesterolemia worldwide, may slow the progression of atherosclerosis and other inflammatory diseases by inhibiting the expression of TLR4 and regulating TLR4/MYD88/NF-κB signaling pathway." (PMID 32002588, 2020). "However, RS-LPS reduced lesion formation in ApoE−/− diabetic mice, suggesting the potential environmental dependence of TLR4 blockade on atherosclerosis." (PMID 32002588, 2020). "TLR4 is important in vascular inflammation, atherosclerosis, and diabetes." (PMID 32823757, 2020). "Thus, finding new therapeutic agents for atherosclerosis by regulating the TLR4 signaling pathway is a rational approach." (PMID 32849545, 2020). "TLR4 is one of the most-reported critical promotors in various processes of atherosclerosis." (PMID 32849545, 2020). "In this study, we found that C8:0, which is a member of the MCFAs, could suppress inflammatory signaling via the TLR4/NF-κB pathway and improve atherosclerosis in apoE−/− mice." (PMID 31182969, 2019). "Moreover, our data offer an explanation for the comparable effects of IFNα or IFNγ priming on TLR4-induced activation in vascular and immune cells, with important implications in atherosclerosis." (PMID 31231385, 2019). "TLR4 has been shown to be involved in the inflammatory response in atherosclerosis." (PMID 31583048, 2019).
atherosclerosis (continued). "Several studies have shown that TLR4 is involved in inflammatory responses in atherosclerosis." (PMID 31583048, 2019). "Therefore, our study provided a novel mechanism that CUMS-induced HMGB1 promotes atherosclerosis via TLR4." (PMID 30881312, 2019). "Given that, we therefore ask whether and how HMGB1 regulates TLR4-mediated inflammation in atherosclerosis induced by CUMS." (PMID 30881312, 2019). "Several studies have confirmed that inflammatory responses mediated by TLR4 may impose significant effects on the initiation and subsequent progression of atherosclerosis." (PMID 31182969, 2019). "The effect of ox-LDL on human atherosclerosis may be at least partially mediated by the TLR4 pathway." (PMID 31583048, 2019). "TLR4 plays an important role in the pathogenesis of atherosclerosis." (PMID 30857550, 2019). "Given that TLR4 is closely related to atherosclerosis, we hypothesized herein that caprylic acid (C8:0) would suppress inflammation via TLR4/NF-κB signaling and further promote the amelioration of atherosclerosis in apoE- deficient (apoE−/−) mice." (PMID 31182969, 2019). "Moreover, it is shown that activation of TLR4 and NF-κB increased the expression of IL-6 and adhesion molecules and decreased the activation of eNOS in atherosclerosis." (PMID 31336567, 2019). "Last, this work should be the first case to indicate that C8:0-mediated inhibition of TLR4/NF-κB signaling may improve atherosclerosis." (PMID 31182969, 2019). "Remaining unknown, however, are TLR4-mediated inflammatory signaling in atherosclerosis and the potential functions." (PMID 31583048, 2019). "Second, it has been shown that modified LDL can bind to TLR4 and promote atherosclerosis." (PMID 30558209, 2018). "The effects of atorvastatin on atherosclerosis may be achieved by the inhibition of the expression of TLR4 and NF-κB p65." (PMID 30497486, 2018). "There are substantial data linking TLR4 with atherosclerosis pathogenesis." (PMID 29649324, 2018). "Contribution of TLR4 signaling in intermittent hypoxia-mediated atherosclerosis progression." (PMID 30142970, 2018). "TLR4 is another portal for macrophages to activate downstream cascades in atherosclerosis lesions." (PMID 29896109, 2018). "The implication of this study is that the deactivation of DC-SIGN or the dissociation of the DC-SIGN/TLR4 complex by synthetic chemicals may effectively attenuate the pathogenesis of atherosclerosis." (PMID 28607410, 2017). "Because TLR4 triggers a pathophysiologically relevant pathway in atherosclerosis, we also determined whether biflavonoids alter the cytokine response to the ligand LPS." (PMID 28824646, 2017). "CREB also increases LPS and TLR4 dependent IL-6 production in vascular smooth muscle cells which may contribute to the vascular inflammation seen in atherosclerosis." (PMID 28545453, 2017). "First, TLR4 can induce the proliferation of vascular smooth muscle cells and upregulate the expression of the elastin-degrading enzyme and cathepsin S that allow smooth muscle cells to migrate to the site of atherosclerosis." (PMID 28002812, 2017). "However, our work revealed that P. gingivalis-mediated TLR4 signaling protects from atherosclerosis, suggesting that effects are pathogen specific." (PMID 28348558, 2017). "Interestingly, endogenous molecules such as high mobility group box 1 (HMGB1) can activate TLR4, which serves as a late mediator of inflammation and contribute to the development of atherosclerosis." (PMID 27563891, 2016). "Some investigators reported a reduced risk of atherosclerosis in carriers of the Asp299Gly TLR4 polymorphism, which was not reproduced in other investigations." (PMID 27795867, 2016). "TLR4 signalling has a critical role in the progression of atherosclerosis and lung inflammation." (PMID 25975841, 2015).
atherosclerosis (continued). "It thus appears that activation of TLR4 is fundamental for atherosclerosis due to its participation in the production of inflammatory cytokines and MMP-9, although other signaling pathways may also be involved." (PMID 25757594, 2015). "Finally, a direct effect on the vascular wall is also possible, as TLR4 has been evidenced in human and murine atherosclerotic plaques, and inhibition of TLR4 signaling pathway attenuated diet-induced atherosclerosis in ApoE−/− mice." (PMID 25873766, 2015). "Collectively, these results indicate that inactivation of TLR4/MyD88-dependent signaling strongly inhibits development of atherosclerosis and promotes a more stable plaque phenotype, mainly by reducing inflammatory molecule release as a consequence of NF-κB inactivation." (PMID 25757594, 2015). "It is well-documented that TLR4 signalling has an important role in atherosclerosis." (PMID 25975841, 2015). "In the context of atherosclerosis, during which inflammatory events are accompanied by oxidative stress, alongside the classic endogenous ligands, oxidized lipids also appear to be capable of activating TLR4 and of modulating an inflammatory response." (PMID 25757594, 2015). "Of note, that newly detected link between CD36 and TLR4/TLR6 activity was described in microglia and monocytes/macrophages activated not by microbial PAMPs but by endogenous ligands whose accumulation is a hallmark of atherosclerosis and Alzheimer’s disease." (PMID 25332099, 2015). "Growing evidence has shown that TLR4 signaling-mediated immune response may play a critical role in the initiation and progression of atherosclerosis." (PMID 25860573, 2015). "The findings of the present study illustrated that TLR4 signalling may be a possible common pathway that contributes to lung injury and atherosclerosis, which may provide valuable information for elucidating the lung-heart cross-talk." (PMID 25975841, 2015). "The activation of Toll-like receptor 4 (TLR4) signaling has an important role in promoting lipid accumulation and pro-inflammatory effects in vascular smooth muscle cells (VSMCs), which facilitate atherosclerosis development and progression." (PMID 26512959, 2015). "It is necessary to consider the potential ligands of TLR4 under stress that may contribute to inflammation and atherosclerosis in CUMS apoE-/- mice." (PMID 25860573, 2015). "In the present study, we first demonstrated the effects of the oxysterol 27-OH and the unsaturated aldehyde HNE on TLR4 activation in human promonocytic U937 cells; both oxidized lipids accumulate in atherosclerotic plaques and play a key role in the pathogenesis of atherosclerosis." (PMID 25757594, 2015). "TLR4/NF-κB pathway may participate in CUMS-induced atherosclerosis through activation of proinflammatory cytokines in apoE-/- mice." (PMID 25860573, 2015). "We hypothesize that CS enhances histamine-mediated upregulation of TLR2/TLR4 signaling in the endothelium and promotes progression of atherosclerosis." (PMID 26617606, 2015). "Previous studies reported that chronic psychological stress could stimulate TLR-4 signaling pathway in various tissues including blood vessels with significant correlation to atherosclerosis." (PMID 25826421, 2015). "Given that the causal relationship between vascular inflammation and atherogenesis, we hypothesized that TLR4/NF-κB pathway might be directly involved in CUMS-induced atherosclerosis." (PMID 25860573, 2015). "Evidence is accumulating that TLR4 plays an important role in the pathogenesis of atherosclerosis." (PMID 25826421, 2015). "Therefore, it is urgent to identify new possibilities to suppress TLR4 signaling during atherosclerosis." (PMID 26492242, 2015). "Furthermore, other common pathognomonic factors such as the Toll-like receptors (TLR2 and TLR4) play key roles in atherosclerosis." (PMID 26339139, 2015).
atherosclerosis (continued). "Based on these immunohistochemistry findings in atherosclerotic patients, we investigated whether TLR4 and inflammatory cytokines are involved in oxLDL-induced atherosclerosis model in mice." (PMID 24755612, 2014). "In conclusion, in the apoE knockout rats, occlusal disharmony may induce VCAM1, ICAM1 and TLR4 expression and accelerate the initiation of atherosclerosis." (PMID 25189624, 2014). "We hypothesize that STAT1-dependent transcriptional changes in vascular cells involved in cross-talk between IFNγ and TLR4, reflect pro-atherogenic responses in human atherosclerosis." (PMID 25478796, 2014). "Taken together, TLR4-mediated expression of Mac-1 in monocytes plays a pivotal role on monocyte adhesion to vascular endothelium, leading to increased foam cell formation in the development of atherosclerosis." (PMID 25116953, 2014). "The clinical implication of this study is that deactivation of TLR4 by humanized antibody could effectively attenuate the pathogenesis of atherosclerosis." (PMID 24755612, 2014). "In apoE knockout rats, occlusal disharmony may induce VCAM1, ICAM1 and TLR4 expression and accelerate the initiation of atherosclerosis." (PMID 25189624, 2014). "In all members of TLRs, TLR4 is the most relevant one with atherosclerosis." (PMID 24755612, 2014). "However, PRRs on endothelial cells, including TLR4 and TLR2, have also been associated with vascular inflammation and cardiovascular disease, such as atherosclerosis." (PMID 24690886, 2014). "TLR4 plays an important role in the initiation of atherosclerosis." (PMID 25189624, 2014). "This could point to the role of IFNγ and TLR4 activation in human atherosclerosis, which is in agreement with previous studies." (PMID 25478796, 2014). "Furthermore, the role played by TLR4 on the modulation of 5-LO suggests an important interaction between 5-LO-mediated inflammation and the development of atherosclerosis." (PMID 25116953, 2014). "Additionally, a previous study documented that common mechanisms of signaling via TLR2, TLR4 and MyD88 link stimulation by multiple pathogens and endogenous ligands to atherosclerosis progression." (PMID 25010102, 2014). "An increase in TLR4 expression was observed in atherosclerosis after oxLDL stimulation." (PMID 23880853, 2013). "There is evidence for a role of TLR4 in the development of human atherosclerosis as well." (PMID 24376657, 2013). "Because BEP-CE is present in human plasma and human atherosclerotic lesions, BEP-CE-induced and TLR4/SYK-mediated macrophage responses may contribute to chronic inflammation in human atherosclerosis." (PMID 24376657, 2013). "We concluded that TLR4/NF-κb/BAFF in macrophages might be a possible common autoimmune pathway that caused lung injury and atherosclerosis." (PMID 24324506, 2013). "Our findings suggest that BEP-CE is an endogenously generated agonist of TLR4 and as such it may contribute to development of atherosclerosis." (PMID 24376657, 2013). "TLR4 signal will be a therapeutic target in atherosclerosis and immune-mediated lung injury." (PMID 24324506, 2013). "In humans, endogenous TLR4 antigens, including fatty acids and oxidized lipids, are generated in obese adipose and atherosclerosis and may drive inflammatory cardio-metabolic dysfunction." (PMID 22709547, 2012). "TLR2, TLR4 and MyD88 have an important role in the development of atherosclerosis characterized by the accumulation of proinflammatory cytokines, chemokines and matrix metalloproteinases (MMPs) mediated by several different cell types in the endothelium of the artery lumen." (PMID 23305364, 2012). "As a receptor of LPS, TLR4 is pivotal in the initiation and development of atherosclerosis." (PMID 23072373, 2012). "Interestingly, transfection of both TLR2 and TLR4 together resulted in a synergistic acceleration of atherosclerosis." (PMID 21526997, 2011). "In mouse atherosclerosis, TLR4 expression is exclusively by macrophages." (PMID 21526997, 2011).
atherosclerosis (continued). "The role of TLR2 and TLR4 has been extensively studied in models of atherosclerosis." (PMID 21526997, 2011). "Indeed, deletion of either TLR-2 or TLR-4 confers a similar degree of protection from lesion development in murine models of atherosclerosis." (PMID 20652007, 2010). "In addition to playing a role in heart failure and myocardial ischemia/reperfusion injury, TLR4 has been found to play a role in neointimal formation, atherosclerosis and stroke." (PMID 20202224, 2010). "TLR4 activity impairs endothelial cell function and contributes to atherosclerosis." (PMID 20814545, 2010). "Indeed, mice deficient in TLR4, TLR2 and MyD88 all have reduced atherosclerosis which establishes that TLR-dependent pathways contribute to disease development." (PMID 18787704, 2008). "Additionally, LPS may promote the progression of atherosclerosis by activating the Toll-like receptor 4 signaling pathway and enhancing platelet aggregation." (PMID 41311477, 2025). "Apolipoprotein E -deficient (ApoE-/-) mice lacking both TLR4 or MyD88 show reduced atherosclerosis." (PMID 39399488, 2024). "Moreover, lycopene administration improved the intestinal barrier function and alleviated intestinal permeability, then reduced serum LPS levels and inhibited cardiovascular inflammation through inactivating the TLR4/NF-κB pathway, thereby inhibiting the progression of atherosclerosis." (PMID 38041095, 2023). "The association between the Asp299Gly (+896A>G; rs4986790) polymorphism in the TLR-4 gene and atherosclerosis risk has been proven by the detection of lower levels of pro-inflammatory IL-6 and TNF-α and higher levels of anti-inflammatory IL-10 in carriers bearing the TLR-4 polymorphism." (PMID 35893405, 2022). "Therefore, inhibition of TLR4 reduce inflammation and delay the progression of atherosclerosis." (PMID 35845572, 2022). "In addition, TLR4 knockdown significantly down-regulates early atherosclerosis in diabetic ApoE−/− mice, which may be related to monocyte activation that is mediated by the TLR4 signaling pathway." (PMID 35062863, 2022). "LPS binds to its binding protein to form the complex and is recognized by TLR4 on the surface of immune cells, followed by neutrophil infiltration and the accumulation of inflammatory factors (TNF-α, IL-1, IL-27, etc.), which increases the risk of atherosclerosis." (PMID 36219347, 2022). "Chronic inflammation, and progressive NIH, and atherosclerosis are associated with vessel thrombosis and stenosis, and increased expression of inflammatory mediators TREM-1, regulated by TLR-4 activation, might play a role in sterile inflammation in AVF maturation failure and patency of AVF." (PMID 36147190, 2022). "In addition to enhancing the activity of GN1, TRIM7 has E3 ubiquitin ligase activity, and through this function, it participates in several processes including glycogen accumulation, cancer development, regulation of atherosclerosis, and of the toll-like receptor 4–mediated innate response." (PMID 33989636, 2021). "Moreover, Tlr4 expression is higher in macrophages in atherosclerotic plaques of ApoE−/− mice on an atherogenic diet and in humans, suggesting that TLR4 represents a pathophysiological link between oxidized lipids, inflammation, and atherosclerosis." (PMID 35083304, 2021).